RHBDL1 (rhomboid like 1)
Description:
Regulator of proteosome activity independent of enzymatic activity. May be involved in regulated intramembrane proteolysis and the subsequent release of functional polypeptides from their membrane anchors.
Synonyms: RRP; RHBDL
Tractability: Antibody: its Gene Ontology location is reachable by antibodies, with high confidence; UniProt predicts a signal peptide or a membrane-spanning region.
Gene: Protein-coding gene on chromosome 16 (675,671 to 678,268, forward strand). Ensembl gene ENSG00000103269.
Subcellular location: Membrane
Subcellular location (Human Protein Atlas): Nucleoplasm
Gene Ontology:
Molecular function: protein binding; serine-type endopeptidase activity
Biological process: signal transduction
Cellular component: membrane; plasma membrane
Genetic constraint (gnomAD): Loss-of-function variants: 22 observed, 33.59 expected, observed/expected ratio (o/e) 0.65, 90% interval 0.47 to 0.94. The synonymous counts are far from expectation, so gnomAD's model fits this gene poorly and the ratio says little. Missense variants: 450 observed, 484.86 expected, observed/expected ratio (o/e) 0.93, 90% interval 0.86 to 1. Synonymous variants: 268 observed, 213.09 expected, observed/expected ratio (o/e) 1.26, 90% interval 1.14 to 1.39.
Homologues: Orthologues: pig RHBDL1 (99% identical), guinea pig RHBDL1 (98% identical), dog RHBDL1 (98% identical), mouse Rhbdl1 (98% identical), rat Rhbdl1 (98% identical), macaque RHBDL1 (97% identical), chimpanzee RHBDL1 (94% identical), tropical clawed frog rhbdl1 (84% identical), zebrafish rhbdl1 (77% identical), Drosophila melanogaster rho-5 (26% identical), Caenorhabditis elegans rom-4 (19% identical), Caenorhabditis elegans rom-3 (14% identical). Paralogues in human: RHBDL3 (56% identical), RHBDL2 (29% identical), RHBDF1 (23% identical), RHBDF2 (22% identical), PARL (13% identical).
Diseases named in the same sentence as RHBDL1 in open-access papers:
RHBDL1 is named in the same sentence as 3 diseases in open-access papers, as found by Europe PMC text mining. Sharing a sentence is not in itself a finding about the gene and the disease. The quoted sentences say what the papers report.
breast carcinoma (1 paper, 2023). "But no previous study has reported the role of PRSS2, SPPL2C and RHBDL1 in breast cancer, thus this study may report the potential role of these genes as independent prognostic predictors in breast cancer for the first time." (PMID 36993976, 2023).
glioma (1 paper, 2023). A benign or malignant brain and spinal cord tumor that arises from glial cells (astrocytes, oligodendrocytes, ependymal cells). "Then, through LASSO regression, 5 genes (ADD3, GRHPR, KLF13, RHBDL1 and SLC9A9) closely related to the prognosis of WHO Grade 4 glioma patients were selected." (PMID 37952042, 2023).
bone disorder (1 paper, 2024). "Notably, genes such as CSRP2, DDX1, RHBDL1, SEZ6L, and CTSK are involved in growth, development, locomotion, and bone disorders." (PMID 38788487, 2024).